THAP4 (THAP domain containing 4)
Description:
Heme-binding protein able to scavenge peroxynitrite and to protect free L-tyrosine against peroxynitrite-mediated nitration, by acting as a peroxynitrite isomerase that converts peroxynitrite to nitrate. Therefore, this protein likely plays a role in peroxynitrite sensing and in the detoxification of reactive nitrogen and oxygen species (RNS and ROS, respectively). Is able to bind nitric oxide (NO) in vitro, but may act as a sensor of peroxynitrite levels in vivo, possibly modulating the transcriptional activity residing in the N-terminal region.
Synonyms: CGI-36; PP238; Nb(III)
Tractability: Small molecule: a structure with a bound ligand is known; it has a binding pocket of medium quality. PROTAC: ubiquitination databases record sites on it.
Gene: Protein-coding gene on chromosome 2 (241,584,405 to 241,637,191, reverse strand). Ensembl gene ENSG00000176946.
Subcellular location: Cytoplasm; Nucleus
Subcellular location (Human Protein Atlas): Cytosol; Nucleoplasm
Gene Ontology:
Molecular function: heme binding; identical protein binding; nitric oxide binding; peroxynitrite isomerase activity; protein binding
Biological process: cellular response to reactive nitrogen species
Cellular component: cytosol; nucleoplasm; cytoplasm; nucleus
Genetic constraint (gnomAD): Loss-of-function variants: 18 observed, 45.65 expected, observed/expected ratio (o/e) 0.39, 90% interval 0.27 to 0.58. The upper end of that interval is the gene's LOEUF score, 0.58, which puts it in group 2 of 6, group 1 being the genes least tolerant of losing a copy. Missense variants: 656 observed, 777.83 expected, observed/expected ratio (o/e) 0.84, 90% interval 0.79 to 0.9. Synonymous variants: 345 observed, 326.01 expected, observed/expected ratio (o/e) 1.06, 90% interval 0.97 to 1.16.
Homologues: Orthologues: chimpanzee THAP4 (99% identical), macaque THAP4 (98% identical), dog THAP4 (86% identical), guinea pig THAP4 (86% identical), pig THAP4 (85% identical), rat Thap4 (84% identical), rabbit THAP4 (84% identical), mouse Thap4 (83% identical), tropical clawed frog stk25 (35% identical), zebrafish thap4 (17% identical), Caenorhabditis elegans F21A3.3 (12% identical).
Diseases named in the same sentence as THAP4 in open-access papers:
THAP4 is named in the same sentence as 1 disease in open-access papers, as found by Europe PMC text mining. Sharing a sentence is not in itself a finding about the gene and the disease. The quoted sentences say what the papers report.
cancer (1 paper, 2025). A tumor composed of atypical neoplastic, often pleomorphic cells that invade other tissues. "For example, THAP4 exhibited a shift in transcript dominance from THAP4-202 (which does not contain the THAP domain) in stem/TA cells (normal epithelial cells) to THAP4-204 (which contain the THAP domain) in stem/TA-like cells (cancer cells)." (PMID 40702779, 2025).